CYP2S1 (cytochrome P450 family 2 subfamily S member 1)
Description:
A cytochrome P450 monooxygenase involved in the metabolism of retinoids and eicosanoids. In epidermis, may contribute to the oxidative metabolism of all-trans-retinoic acid. For this activity, uses molecular oxygen inserting one oxygen atom into a substrate, and reducing the second into a water molecule, with two electrons provided by NADPH via cytochrome P450 reductase (NADPH--hemoprotein reductase). Additionally, displays peroxidase and isomerase activities toward various oxygenated eicosanoids such as prostaglandin H2 (PGH2) and hydroperoxyeicosatetraenoates (HPETEs). Independently of cytochrome P450 reductase, NADPH, and O2, catalyzes the breakdown of PGH2 to hydroxyheptadecatrienoic acid (HHT) and malondialdehyde (MDA), which is known to act as a mediator of DNA damage.
Synonyms: CYPIIS1
Tractability: Small molecule: it belongs to a druggable protein family. Antibody: UniProt places it where antibodies can reach, with high confidence. PROTAC: its protein half-life has been measured; a small molecule that binds it is known.
Gene: Protein-coding gene on chromosome 19 (41,193,045 to 41,207,540, forward strand). Ensembl gene ENSG00000167600.
Subcellular location: Endoplasmic reticulum membrane; Microsome membrane
Subcellular location (Human Protein Atlas): Endoplasmic reticulum
Pathways (Reactome):
Metabolism: CYP2E1 reactions; Miscellaneous substrates; Xenobiotics
Gene Ontology:
Molecular function: 12-hydroxyheptadecatrienoic acid synthase activity; hydro-lyase activity; monooxygenase activity; protein binding; thromboxane-A synthase activity; arachidonate epoxygenase activity; heme binding; oxidoreductase activity, acting on paired donors, with incorporation or reduction of molecular oxygen, reduced flavin or flavoprotein as one donor, and incorporation of one atom of oxygen; retinoic acid 4-hydroxylase activity; hydroperoxy icosatetraenoate dehydratase activity; iron ion binding; oxidoreductase activity, acting on paired donors, with incorporation or reduction of molecular oxygen
Biological process: icosanoid metabolic process; prostaglandin metabolic process; retinoic acid metabolic process; cytochrome metabolic process; epoxygenase P450 pathway; xenobiotic metabolic process; fatty acid metabolic process
Cellular component: endoplasmic reticulum; endoplasmic reticulum membrane; cytoplasm
Genetic constraint (gnomAD): Loss-of-function variants: 32 observed, 43.3 expected, observed/expected ratio (o/e) 0.74, 90% interval 0.56 to 0.99. The upper end of that interval is the gene's LOEUF score, 0.99, which puts it in group 4 of 6, group 1 being the genes least tolerant of losing a copy. Missense variants: 575 observed, 669.36 expected, observed/expected ratio (o/e) 0.86, 90% interval 0.8 to 0.92. Synonymous variants: 283 observed, 296 expected, observed/expected ratio (o/e) 0.96, 90% interval 0.87 to 1.05.
Homologues: Orthologues: chimpanzee CYP2S1 (99% identical), macaque CYP2S1 (96% identical), rabbit CYP2S1 (79% identical), guinea pig CYP2S1 (79% identical), pig CYP2S1 (78% identical), mouse Cyp2s1 (78% identical), rat Cyp2s1 (76% identical), dog CYP2S1 (75% identical). Paralogues in human: CYP2B6 (48% identical), CYP2A13 (47% identical), CYP2A6 (46% identical), CYP2A7 (46% identical), CYP2F1 (45% identical), CYP2C19 (43% identical), CYP2C9 (43% identical), CYP2C18 (43% identical), CYP2C8 (42% identical), CYP2E1 (39% identical), CYP2W1 (38% identical), CYP2U1 (37% identical), and 3 more.
Diseases named in the same sentence as CYP2S1 in open-access papers:
CYP2S1 is named in the same sentence as 28 diseases in open-access papers, as found by Europe PMC text mining. Sharing a sentence is not in itself a finding about the gene and the disease. The quoted sentences say what the papers report.
breast carcinoma (5 papers, 2017 to 2025). "Low cytoplasmic CYP2S1 was significantly associated with adverse breast cancer specific survival in ER‐positive patients (p = 0.031), but not in ER‐negative disease (p = 0.197)." (PMID 35902379, 2022). "Immunohistochemical analysis of CYP2S1 conducted in 170 breast cancers reported that high expression was associated with shorter patient survival, although this was not confirmed in multivariate analysis." (PMID 35902379, 2022). "Low cytoplasmic CYP2S1 was significantly associated with adverse breast cancer specific survival (p = 0.034), which remained so in multivariate analysis (hazard ratio [HR]: 0.639; 95% confidence interval [CI]: 0.483–0.846; p = 0.002)." (PMID 35902379, 2022). "In the molecular taxonomy of breast cancer international consortium (METABRIC) cohort, high CYP2S1 mRNA was significantly associated with basal like breast cancers compared to CYP2W1 which was predominantly expressed in luminal A tumours (SM and RA unpublished data)." (PMID 33809117, 2021). "As was mentioned in the previous section, CYP2S1 expression was found in breast cancer cells differing in hormone receptor status." (PMID 41020804, 2025). "As was mentioned in Section 2, orphan CYP2S1 was reported to be upregulated in breast cancer cells and clinical samples." (PMID 41020804, 2025). "High expression of nuclear CYP2S1 and of CYP2W1 (p = 0.006) was also significantly associated with adverse breast cancer specific survival (p = 0.006)." (PMID 35902379, 2022). "Gene knockdown studies in breast cancer cells identified the role of CYP2S1 in metabolically inactivating benzothiazoles while induction of CYP1A1 remained crucial for their activation and anti-tumour properties." (PMID 33809117, 2021). "A study conducted in 170 breast carcinomas reported that absence of CYP2S1 expression was associated with better survival of breast cancer patients." (PMID 35902379, 2022). "CYP2S1 and CYP2W1 are associated with patient survival in breast cancer and may be important prognostic biomarkers." (PMID 35902379, 2022). "Low cytoplasmic, but not nuclear, expression of CYP2S1 was significantly associated with poor breast cancer specific survival (p = 0.034) in the total patient cohort." (PMID 35902379, 2022). "Low cytoplasmic CYP2S1 and nuclear CYP2W1 expression (p = 0.035), and high nuclear CYP2S1 and cytoplasmic CYP2W1 expression (p = 0.023), were significantly associated with adverse breast cancer specific survival in the total patient cohort." (PMID 35902379, 2022). "Similarly, CYP2J2 and CYP2S1 expression in breast cancer models could influence drug metabolism and treatment response." (PMID 41174467, 2025). "Breast cancer models, particularly MCF-7 cells, exhibited a different CYP450 profile, with CYP2J2, CYP2S1, CYP2A6 and CYP2A13 being the most prominent isoforms." (PMID 41174467, 2025). "Breast cancer models predominantly expressed CYP2J2 and CYP2S1, whereas CYP3A and CYP2C subfamily members were enriched in hepatic cancer, underscoring their roles in xenobiotic metabolism and drug clearance." (PMID 41174467, 2025). "In some smaller pools of patients, increased transcript levels of CYP2S1, CYP2W1, and CYP4F11 were found in breast cancer, adjacent, and normal breast cells." (PMID 41020804, 2025). "The others, such as CYP2W1, CYP2S1, CYP2U1, CYP4X1, and CYP4V2, are less specific, but their overexpression in breast cancer has also been found." (PMID 41020804, 2025). "In the most extensively investigated ER(+) MCF7 breast cancer cell line, the expression of three orphan CYPs, namely CYP4Z1, CYP2S1, and CYP2W1, was confirmed by several authors." (PMID 41020804, 2025). "Future studies should assess larger patient cohorts to determine the clinical utility of using CYP2S1 and CYP2W1 as biomarkers, including examining their role in the hormonal and chemotherapeutic response of breast cancer patients." (PMID 35902379, 2022).
breast carcinoma (continued). "The aim of the study was to investigate the protein expression of CYP2S1 and CYP2W1 in a large independent cohort of breast cancer patient tumour samples by immunohistochemistry." (PMID 35902379, 2022). "mRNA expression of CYP2S1 and CYP2W1 was also assessed in the Molecular Taxonomy of Breast Cancer International Consortium (METABRIC) cohort." (PMID 35902379, 2022). "CYP2S1 and CYP2W1 mRNA expression was also evaluated in a separate cohort of patients, the Molecular Taxonomy of Breast Cancer International Consortium (METABRIC) cohort." (PMID 35902379, 2022). "Current literature supports the findings in the present study that low expression of cytoplasmic CYP2S1 and of nuclear CYP2W1 results in shorter survival of breast cancer patients, a trend which was maintained even in multivariate analysis." (PMID 35902379, 2022). "Although the prognostic values of CYP2S1 and CYP2W1 have been studied in other cancers, such as colon, there is little information regarding the prognostic value of CYP2S1 and CYP2W1 in breast cancers." (PMID 35902379, 2022). "The benzothiazole 5F203 (and analogue GW-610) was found to selectively induce the expression of CYP2S1 and CYP2W1 in isogenic breast cancer cells depleted for the isoforms." (PMID 33809117, 2021). "In breast cancer cell lines MCF-7 and MDA-MB-231, constitutive expression of both CYP2S1 and CYP2W1were detected, with greater abundance in MDA-MB-231 cells." (PMID 33809117, 2021). "Similarly to CYP2S1, the expression of CYP2W1 was described in breast cancer cells differing in hormone receptor status, and its upregulation was found in breast cancer samples." (PMID 41020804, 2025). "None of the combined groupings of cytoplasmic and nuclear CYP2S1 or CYP2W1 showed any significant associations in ER‐negative (p = 0.194) or ER‐positive breast cancers (p = 0.354) respectively." (PMID 35902379, 2022). "In addition to looking at single marker expression, combined expression of both CYPs (CYP2S1 and CYP2W1) was also examined to assess the effects of marker combinations on breast cancer specific survival." (PMID 35902379, 2022). "The orphan CYPs, CYP2S1, and CYP2W1 are reportedly upregulated in breast cancer." (PMID 35902379, 2022).
colorectal cancer (5 papers, 2016 to 2025). A primary or metastatic malignant neoplasm that affects the colon or rectum. "Database analysis revealed that CYP2S1 was upregulated in colorectal cancer and positively associated with better prognosis." (PMID 40740230, 2025). "CYP2S1, described as Cytochrome P450 Family 2 Subfamily S Member 1, was reported significantly associated with colorectal cancer." (PMID 32854645, 2020). "Furthermore, Kaplan-Meier survival analysis demonstrated that high CYP2S1 expression was positively associated with better prognosis in patients with colorectal cancer." (PMID 40740230, 2025). "Using the TIMER2.0 database, we found that CYP2S1 was significantly upregulated in colorectal cancer tissues compared to adjacent normal tissues." (PMID 40740230, 2025). "In conclusion, these findings suggest that CYP2S1 represents a promising biomarker and therapeutic target for improving the prognosis and treatment of colorectal cancer." (PMID 40740230, 2025). "Our findings demonstrate that CYP2S1 knockout enhances tumor progression in APCMin/+ mice and elucidates its impact on colorectal cancer cell proliferation and migration." (PMID 40740230, 2025). "In summary, these in vitro results showed that CYP2S1 silencing promoted the proliferation, migration and invasion of colorectal cancer cells, consistent with above mouse experiments." (PMID 40740230, 2025). "In conclusion, the key point of this study is that knockout of CYP2S1 can promote the development of colorectal cancer." (PMID 40740230, 2025). "In primary colorectal cancer, CYP2S1 was present at a significantly higher level of intensity compared with normal colon." (PMID 32854645, 2020). "We selected highly expressed colorectal cancer HT29 cells for CYP2S1 silencing." (PMID 40740230, 2025). "In this study, we constructed APCMin/+;CYP2S1-/- hybrid mice to study colorectal cancer." (PMID 40740230, 2025). "Furthermore, increased expression of PGE2 (regulated by CYP2S1) was found to increase cellular proliferation in colorectal cancer cells." (PMID 35902379, 2022). "To determine whether oxaliplatin treatment induces CYP2S1 expression, we treated colorectal cancer cell lines with an oxaliplatin dose that reflects the peak plasma concentration reported in clinical 24 h-measurements." (PMID 27609465, 2016). "However, the specific function and mechanism of CYP2S1 in colorectal cancer remain elusive." (PMID 40740230, 2025). "However, our ex vivo and in vivo experiments confirmed that CYP2S1 silencing promotes colorectal cancer, suggesting that CYP2S1 may be a cancer suppressor gene." (PMID 40740230, 2025). "We also did not further verify whether CYP2S1 deficiency activates the Wnt signaling pathway to promote the occurrence and development of colorectal cancer." (PMID 40740230, 2025). "Therefore, the characterization of CYP2S1 in the process of influencing oxaliplatin activity may lead to potential strategies for colorectal cancer treatment." (PMID 27609465, 2016). "The RNF43-, CYP2S1- and LIF-related super-enhancers are shown as colorectal cancer–specific super-enhancers since the odds ratio of these three gene-related super-enhancers are >20 (P < 0.05) in primary tissues and >15 in cell lines (P < 0.05)." (PMID 37207350, 2023). "CYP2S1 and CYP2W1 are also involved in the metabolism of 5F‐203 and GW‐610 in breast and colorectal cancer cells." (PMID 35902379, 2022).
colorectal cancer (continued). "In vitro, we found that CYP2S1 knockout could increase proliferation and migration in CYP2S1-silenced HT29 cells, indicating that CYP2S1 deletion promotes the occurrence and development of colorectal cancer." (PMID 40740230, 2025).
psoriasis (5 papers, 2013 to 2024). An autoimmune condition characterized by red, well-delineated plaques with silvery scales that are usually on the extensor surfaces and scalp. "Studies have reported elevated levels of CYP2S1 in psoriasis, a condition that is mainly characterised by hyper‐proliferation of keratinocytes." (PMID 35902379, 2022). "CYP2S1 expression is elevated in multiple epithelial-derived cancers as well as in the chronic hyperproliferative disease psoriasis." (PMID 24279958, 2013). "CYP2S1 was also elevated in chronic hyperproliferative diseases, including psoriasis as well as multiple epithelial cancers." (PMID 24279958, 2013). "Other differentially methylated loci in psoriatic lesions compared with the normal skin of patients with psoriasis and with normal skin from healthy controls are S100A8 (involved in epidermal differentiation), CYP2S1 (metabolism of retinoic acid), and EIF2C2 (with a role in RNA processing)." (PMID 37628670, 2023). "It has been demonstrated that in psoriasis-affected skin, the gene expression of CYP2S1, ECE1, EIF2C2, MAN1C1, and DLGAP4 is negatively correlated with DNA methylation, with a particular focus on intragenic hypomethylation of CYP2S1, highlighting the need for further investigation in the future." (PMID 38612637, 2024).
colon cancer (3 papers, 2020 to 2025). "In vitro, silencing CYP2S1 increased the proliferation and migration of the colon cancer cell line HT29." (PMID 40740230, 2025).
Breast Tumors (2 papers, 2014 to 2025). "Although less specific, the other orphan CYPs, such as CYP2W1, CYP2S1, CYP2U1, and CYP4X1, exhibit significantly higher expression in breast tumors compared to normal tissues." (PMID 41020804, 2025).
lung carcinoma (2 papers, 2006 to 2023). "Regarding the functional role of CYP2S1 in the tumorigenesis process, Guo and co-workers reported that CYP2S1 knockdown reduced the proliferation, invasion, and migration of lung cancer cells." (PMID 38001897, 2023). "Moreover, the inhibition of CYP2S1 expression in animal models decreased the growth of lung cancer." (PMID 38001897, 2023).
melanoma (2 papers, 2020 to 2022). A malignant, usually aggressive tumor composed of atypical, neoplastic melanocytes. "CYP2S1 expression was not clearly associated with BRAFV600E mutation in melanomas and lung adenocarcinomas." (PMID 32913191, 2020). "In contrast to renal cancer model, no expression of Cyp2s1 could be detected in the melanoma cells, in both culture conditions." (PMID 35163092, 2022).